NLRP3 (NLR family pyrin domain containing 3)
Diseases named in the same sentence as NLRP3 in open-access papers (continued):
Sharing a sentence is not in itself a finding about the gene and the disease.
COVID-19 (continued). "To investigate if NLRP3 inflammasome participates in the genesis of the inflammatory process induced by the SARS-CoV-2 or if it is only an additional marker of inflammation, we performed in vivo infections in a mouse model of COVID-19." (PMID 38838044, 2024). "Therefore, inhibition of the NLRP3 inflammasome could potentially lead to a corresponding decrease in the levels of strongly pro-inflammatory cytokines, especially IL-1β, which is released from pyroptotic macrophages and monocytes in large amounts in COVID-19 ARDS." (PMID 39051370, 2024). "The involvement of the NLRP3 inflammasome in the pathogenesis of COVID-19 was postulated based on early clinical observations of the increased IL-1 signaling and high lactate dehydrogenase (LDH) levels in severe COVID-19." (PMID 38664396, 2024). "In similar studies, SFN was found to inhibit NLRP3 inflammasome activation without the involvement of the Nrf2 pathway, thereby modulating cytokine storms in patients with COVID-19." (PMID 39459194, 2024). "The failure of antivirals to solve the problem of preventing COVID-19 complications is due to the fact that there is no direct link between viral replication and the hyperresponsiveness of the NLRP3 inflammasome." (PMID 39064010, 2024). "Additionally, the distribution of the haplotypes of NLRP3, NLRC4, NLRP1, CARD8, CASP1, IL1B, and ATG16L1, with a frequency greater than 5% in HC, were similar between COVID-19 patients with mild, moderate, severe, and critical infection, and HC." (PMID 38612539, 2024). "Thus, we assessed the regulation of the NLRP3 subunit and its downstream effector caspase 1, in the in vitro HPMVEC COVID-19 model." (PMID 38771750, 2024). "Given the growing body of evidence linking dysregulated immune responses and cytokine storm to severe COVID-19 outcomes, investigating the gene expression of NLRP1, NLRP3, and ASC, as well as the serum levels of IL-1β, in patients with COVID-19 is of paramount importance." (PMID 37723427, 2023). "The NLRP3-specific inhibitor MCC950 and caspase-1 inhibitor Ac-YVAD significantly blocked the N-protein-induced NLRP3 inflammasome induction, suggesting the therapeutic potential of these inhibitors against COVID-19." (PMID 37243203, 2023). "In contrast, the NLRP3 inflammasome was found activated in response to SARS-CoV-2 infection and identified in peripheral blood mononuclear cells (PBMCs) and postmortem tissues of COVID-19 patients." (PMID 37711609, 2023). "At the cellular level, contradictory results have been published with reports describing either enhanced NLRP3 inflammasome activation in monocytes and polymorphonuclear cells (PMN) from COVID-19 or septic patients, while other articles rather described decreased responses." (PMID 38140660, 2023). "Previously, activation of the NLR family pyrin domain containing 3 (NLRP3) inflammasome, a major driver of inflammation, has been observed in the lungs, sera and peripheral blood mononuclear cells (PBMCs) of patients with COVID-19." (PMID 36894537, 2023). "Indeed, inflammation, and in particular the NLRP3-interleukin pathway is known to affect outcomes in both ACS and COVID-19." (PMID 37900573, 2023). "mRNA expression of ASC (P = 0.008) and NLRP1 (P = 0.03) gene had a significant increase in COVID-19 patients compared to HS, while there was no significant increase in the expression of NLRP3 between the studied group." (PMID 37723427, 2023). "The stimulation with recombinant SARS-CoV-2 S protein induces NLRP3 activation in macrophages derived from COVID-19 patients but not healthy individuals." (PMID 36703213, 2023). "NLRP3-dependent inflammasome activation and uncontrolled extracellular traps (NET) production by neutrophils have been proposed to contribute to hyper-inflammation and dysregulated coagulation in COVID-19 patients with severe disease." (PMID 37920468, 2023).
COVID-19 (continued). "While the NLRP3 mRNA level had an up-regulation in the COVID-19 patients compared to HS group, this elevation was not statistically significant (P = 0.16)." (PMID 37723427, 2023). "In addition, other works supporting these data have already demonstrated inflammasome NLRP3 assembly and activation in human primary monocytes infected with SARS-CoV-2 and PBMCs from COVID-19 patients." (PMID 37669865, 2023). "Furthermore, the expression levels of NLRP3, NLRP6, IL-1β, and MARCH7 were decreased in COVID-19 patients, while they rose again in convalescent patients." (PMID 38004809, 2023). "It was demonstrated that monocytes in COVID-19 patients are the outposts of SARS-CoV-2 invasion via TLR sensing and can release inflammatory cytokines by assembling NLRP3, activating caspase-1 to generate a “cytokine storm,” and synthesizing GSDMD-NT to induce cellular pyroptosis." (PMID 36532040, 2022). "In a proteomic analysis by mass spectrometry, we did not detect NLRP3, caspase-1, IL-1β, or NF-κB proteins in the COVID-19 patient exosomes." (PMID 35587188, 2022). "In this review, we discussed the lncRNA expression profiles in both non-severe and severe COVID-19 cases, as well as the involvement of lncRNAs in lymphopenia, neutrophilia, NLRP3 activation, IL-6 dysregulation, and IFN-I response delay." (PMID 36052163, 2022). "Molecular docking showed that N-0385 could block SARS-CoV-2 infection and treat COVID-19 by acting on ACE2, TMPRSS2 and NLRP3." (PMID 36329841, 2022). "Following NLRP3 inflammasome action is the downstream release of DAMPs (i.e., the excess release of nuclear protein high-mobility group box 1 (HMGB1]) through GSDMD, as demonstrated by the hyperinflammation during viral infection and/or COVID-19." (PMID 35328506, 2022). "Notably NLRP3 activation is central to inflammation and the pathogenesis of ARDS in severe COVID-19." (PMID 36143338, 2022). "Here, we observed an increased NLRP3/ASC punctate structures formation in COVID-19/B.1 patients (p < 0.0001 vs. control patients) and overexpressed in COVID-19/B1.1.7 patients (p < 0.0001 vs. COVID-19/B.1 patients)." (PMID 36498845, 2022). "ASC spots were colocalized with AIM2 and NLRP3 spots in almost all monocytes of COVID-19 patients, but their function is not clear." (PMID 36389144, 2022). "While a recent report showed high levels of NLRP3 inflammasome and caspase 1 expression in lungs with fatal COVID, the status of the NLRP3 inflammasome on the pulmonary vascular wall in COVID-19 is not known." (PMID 35144622, 2022). "Patients with coronavirus disease 2019 (COVID-19) exhibited activated toll-like receptors (TLRs) and the Nucleotide-binding and oligomerization domain (NOD-), leucine-rich repeat (LRR-), pyrin domain-containing protein 3 (NLRP3) inflammasome." (PMID 35639261, 2022). "NLRP3 inflammasome activation primed and stimulated host inflammatory response, and the inflammatory cytokines (including IL-1β, IL-2, IL-6, IL-8, IL-18, and TNF-α) have been identified to be related to disease severity in COVID-19 patients." (PMID 34979342, 2022). "Furthermore, after the identification of an FDA-approved inhibitor of the NLRP3-specific regulatory protein Bruton ́s tyrosine kinase (BTK), the application of the commercially available BTK inhibitor ibrutinib in severe COVID-19 cases was investigated." (PMID 35626754, 2022). "In response to the SARS-CoV-2 S protein, NLRP3 expression and IL-1β release are upregulated in macrophages from patients with COVID-19 but not in macrophages from healthy patients." (PMID 36419185, 2022). "Heightened expression of the NLRP3 inflammasome was detected in leukocytes in the lungs of all patients who did not survive COVID-19." (PMID 35897696, 2022). "The causes of age-related differences in early immune response in SARS-CoV-2 are still being studied, and there is no definite evidence that the activation of NLRP3 inflammasome is beneficial to COVID-19 in children." (PMID 36248872, 2022).
COVID-19 (continued). "Thus, on the one hand an overlap exists between the pathophysiology of COVID-19 and AID such as NLRP3-inflammasomopathies." (PMID 36034552, 2022). "Indeed, similar to our findings, NLRP3 in SARS-Cov-2-infected patients is activated already in PBMCs, and its expression correlates with serum markers of COVID-19 severity." (PMID 35190924, 2022). "Besides activation of the NLRP3 inflammasome and HMGB1, hypoxia-inducible factor-1α (HIF-1α) signaling pathway is also elevated in elderly patients with COVID-19." (PMID 35356515, 2022). "NLRP3 assembly with consequent activation of caspase-1 and downstream consequences like increased active TNF-alpha, IL-1beta and IL-18 are increased in the lungs of fatal COVID-19 cases." (PMID 36555204, 2022). "Finally, specific inhibition of the NLRP3 inflammasome by MCC950 alleviated excessive lung inflammation and thus COVID-19 like pathology in human ACE2 transgenic mice." (PMID 34979342, 2022). "In this study, the top 11 hub genes pathways of COVID-19, RA, and pyroptosis were enriched in the Network map of the SARS-CoV-2 signaling pathway, Activation of the NLRP3 inflammasome by SARS-CoV-2, IL, NF-κB, TNF signaling pathway and regulation of cytokine-mediated signaling pathway." (PMID 36532040, 2022). "The expression of NLRP3 pathway components was higher in lungs from COVID-19 ARDS subjects as compared to non-COVID-19 non-ARDS cases." (PMID 35144622, 2022). "Hydroxychloroquine and colchicine are anti-NLRP3 inflammasome agents and have been tested in clinical trials against COVID-19; however, the completion point has not been reached." (PMID 35233748, 2022). "Innate immune receptor activation or inactivation has not been studied extensively for severe COVID-19-associated ARDS, but consistent evidence exists for the activation of TLR4, TLR7 and NLRP3." (PMID 33672738, 2021). "In this study, microscopic analysis in combination with luminescent assays show the formation of NLRP3 and ASC puncta, caspase-1 activation, and IL-1β secretion in PBMCs (Peripheral blood mononuclear cells) of COVID-19 patients during the disease and in postmortem lung tissues." (PMID 33467177, 2021). "Similarly, inflammasome components, including NLRP3, ASC specks, and caspase-1, are found in leukocytes of post-mortem lung samples of patients with fatal cases of COVID-19." (PMID 34360684, 2021). "The World Health Organization reported that most repositioned drugs modulators, under clinical investigation against COVID-19, act through different pathways such as UPR, autophagy, the NLRP3 inflammasome, and mitochondrial permeability transition pores [MPTP]." (PMID 34360945, 2021). "For example, in severe COVID-19, TLR7 (viral) and TLR4 (bacterial/fungal) synergize, TLR9 and TLR4 (both bacterial/fungal) synergize and TLR2 and TLR4 (both bacterial/fungal) synergize with NLRP3 (viral and bacterial)." (PMID 33672738, 2021). "In addition, the mRNA level of the inflammasome component NLRP3 and the enhanced production of IL-1β are reversed by treatment with 25-HC@DDAB in PBMCs from patients with severe COVID-19." (PMID 34360684, 2021). "The present study aimed to investigate whether serum levels of NLRP3, HMGB1, IL-6, IL-10, angiotensin II and ACE2 were different in COVID-19 patients with headache." (PMID 34384355, 2021). "In COVID-19, increased expression of ACE2 in obese subjects contributes to activation of the NLRP3 inflammasome and hyperproduction of pro-inflammatory cytokines that are superimposed on the chronic inflammatory state to promote the cytokine shock characteristic of severe COVID." (PMID 33668493, 2021). "The NLRP3 pathway components were significantly higher in lungs from COVID-19 subjects as compared to non-COVID-19 fatal cases without respiratory disease." (PMID 34494018, 2021).
COVID-19 (continued). "The World Health Organization reported that most repositioned drugs modulators, under clinical investigation against COVID-19, act through different pathways such as UPR, autophagy, the NLRP3 inflammasome, and mitochondrial permeability transition pores (MPTP) to inhibit SARS-COV2 propagation." (PMID 34360945, 2021). "Since NLRP3 inflammasome is well controlled in most patients with COVID-19, cytokine storm is not common." (PMID 34150848, 2021). "The NLRP3 (NOD-, LRR- and pyrin domain-containing protein 3) and MyD88 (myddosome) are key mediators upstream of cytokines storm involved in acute respiratory distress syndrome, VTE, myocarditis, and heart failure in COVID-19." (PMID 33182653, 2020). "Noteworthy, animal experiments have shown that MET can inhibit NLRP3 inflammasome activation by suppressing mitochondrial ATP and DNA synthesis, protecting mice against LPS-induced acute respiratory distress syndrome (ARDS) and attenuating pulmonary inflammation in COVID-19-infected mice." (PMID 40175524, 2025). "As a result, HIF may be intensely activated in group A, potentially triggering the NLRP3 inflammasome as a consequence of hypoxia rather than directly due to COVID-19." (PMID 40004007, 2025). "Given that SARS-CoV-2 amplifies NLRP3 activation, we hypothesize that obese patients with COVID-19 will exhibit greater NLRP3 inflammasome activation compared to obese patients without COVID-19." (PMID 40004007, 2025). "Although statins may instigate SREBP2-dependent NLRP3 inflammasome activation in PBMCs, this does not appear to impact significantly in the various statin-related epidemiological studies in larger COVID-19 cohorts." (PMID 38388172, 2024). "Hence, we looked for a possible association between the NLRP3 inflammasome pathway activation and IFN signaling in our cohort of COVID-19 patients admitted to ICU in the presence and absence of VitD3 administration." (PMID 38748756, 2024). "In addition, we observed a positive correlation between the amount of NLRP3 and ASC puncta with the time of disease, thus suggesting that whereas the viral load is reduced, inflammasome activation increases during hospitalization in lethal cases of COVID-19." (PMID 38838044, 2024). "Here, we have shown both in vitro and using a cohort of COVID-19 hospitalized patients with or without VitD3 treatment, that VitD3 exhibits an anti-inflammatory activity by targeting the NLRP3 inflammasome pathway at both transcriptional and translational levels." (PMID 38748756, 2024). "For this, we have measured the expression of the different players implicated in the NLRP3 inflammasome pathway including NLRP3, CASP-1, ASC, IL-1β and IL-18 in whole blood of severe COVID-19 patients treated or not with 50,000 IU cholecalciferol once per week for 2–3 weeks during their stay at ICU." (PMID 38748756, 2024). "Moreover, exosomes from patients with severe COVID-19 (but not light COVID-19 or healthy donors) induced the expression of NLRP3, pro-caspase-1 and pro-IL-1β in human endothelial cells, microvascular endothelial cells and liver endothelial cells." (PMID 38439942, 2023). "The absence of significant changes in NLRP3 expression and IL-1β levels might reflect the complexity of the immune response in COVID-19." (PMID 37723427, 2023). "However, the lack of significant change in NLRP3 expression and serum IL-1β levels between COVID-19 cases and HS is intriguing." (PMID 37723427, 2023). "Besides NLRP3, other types of inflammasomes that were initially known to interact with dsRNA or bacteria such as AIM-2, caspase-4 and -8 were found to play a role in the inflammation responses during COVID-19." (PMID 37360532, 2023). "In addition, activation of NLRP3 inflammasome by SARS-CoV-2 (P = 0.003) and host–pathogen interaction of human coronavirus interferon induction (P < 0.0001) canonical pathways was upregulated in T cells of COVID-19 subjects vs. healthy controls." (PMID 36881624, 2023).
COVID-19 (continued). "A wide variety of cardiovascular diseases after SARS-Cov-2 infection have been reported, including myocarditis, and the NLRP3 inflammasome may be activated by SARS-Cov-2 infection and participate in the progression of Corona Virus Disease 2019 (COVID-19)-related myocarditis." (PMID 37256114, 2023). "Accordingly, the inhibition of NLRP3 reduces the cytokine storm and lung injury induced by SARS-CoV-2 infection, suggesting that the development of NLRP3 inhibitors for clinical use in COVID-19 may prove valuable." (PMID 37508374, 2023). "Additionally, the ASC and NLRP1 gene expression were increased significantly in COVID-19 patients compared to HS, whereas there was no significant increase in the expression of NLRP3 between the investigated group." (PMID 37723427, 2023). "However, there is a lack of direct evidence on the role of the NLRP3 inflammasome in COVID-19-related myocarditis, and further research is needed to better understand COVID-19-related myocarditis." (PMID 37256114, 2023). "Therefore, inhibition of NLRP3 activation and GSDMD cleavage may also be a potential therapy for COVID-19." (PMID 37631016, 2023). "Additionally, it has been suggested that CD147 as an entry receptor for SARS-CoV-2 enables the virus to penetrate the infected cell cytoplasm and activate the NLR family pyrin domain containing 3 (NLRP3) inflammasome that cleaves IL-1ß and IL-18 in COVID-19 patients." (PMID 37016434, 2023). "Although a direct link between NLRP3-mediated pyroptosis and ibrutinib treatment has not been established yet, the promising results call for further investigation of a broader ibrutinib treatment of COVID-19 patients." (PMID 35626754, 2022). "This elaborate mechanism, together with our in vivo study, jointly supported the promise of the NLRP3 inflammasome as a valid target in treating COVID-19 related immune activation although we did not perform an assay to verify the binding of NLPR3 with ASC in our system." (PMID 34979342, 2022). "The NLRP-3 (or NALP) inflammasome complex is a multiprotein complex mediated and activated by both ACE2 and TMPRSS2, and it may have a central role in the disproportionate cytokine release and immunothrombotic COVID-19 repercussions." (PMID 36361818, 2022). "Considering the potential function of NLRP3 in SARS-CoVs infection-mediated inflammatory responses, blocking inflammatory cytokines and the NLRP3 inflammasome may be a promising strategy for limiting the effects of COVID-19." (PMID 34199223, 2021). "On the other hand, IL-6 and ACE2 were found to be successful in classifying COVID-19 patients with headache (SeIL-6: 0.82; SpIL-6:0.48) (SeACE2: 0.79; SpACE2: 0.53), while NLRP3 was successful in classifying COVID-19 patients without headache (SeNLRP3: 0.38; SpNLRP3:0.93)." (PMID 34384355, 2021). "Several important pathways, including those, TXNIP-NLRP3, NLRP3 inflammasome, SIRT1/ NLRP3 pathway, NLRP3 inflammasome components, TH17/Treg, proinflammatory cytokines and inflammatory mediators, have been identified as potential targets of Quercetin to manage COVID-19." (PMID 33509217, 2021). "Indeed, NLRP3 and ASC specks were also observed in postmortem lung tissues from COVID-19 patients." (PMID 34977191, 2021). "Furthermore, NLRP1-dependent pyroptosis is sufficient to cause progressive lung injury, independent of NLRP3 activation or IL-1b secretion, which suggests a relevant role of DPP9 in mediating lung injury seen in severe COVID-19." (PMID 34027315, 2021). "The NLRP3 inflammasome activation in lipopolysaccharide-primed macrophages was shown to be induced by SARS-CoV 3a; AGEs may escalate COVID-19 severity in elderly people by hindering NLRP3 inflammasome-mediated innate immune responses during the early stages of viral infection." (PMID 34204163, 2021).